DSCR8 (Down syndrome critical region 8)
Synonyms: MMA-1; C21orf65; MTAG2; CT25.1a; CT25.1b; MMA-1a; MMA-1b; MMA1
Gene: Long non-coding RNA gene on chromosome 21 (38,121,441 to 38,156,511, forward strand). Ensembl gene ENSG00000198054.
Diseases named in the same sentence as DSCR8 in open-access papers:
DSCR8 is named in the same sentence as 12 diseases in open-access papers, as found by Europe PMC text mining. Sharing a sentence is not in itself a finding about the gene and the disease. The quoted sentences say what the papers report.
hepatocellular carcinoma (7 papers, 2018 to 2022). A malignant tumor that arises from hepatocytes. "Increased expression of DSCR8 is associated to malignant pathology and poor survival in hepatocellular carcinoma (HCC) patients." (PMID 32591022, 2020). "On the other hand, lncRNA DSCR8 has been found overexpressed in hepatocellular carcinoma (HCC) and promotes proliferation and migration of HCC cells by regulating miR-485-5p and Wnt/β-catenin signaling pathway." (PMID 32984052, 2020). "DSCR8 has been found to mediate hepatocellular carcinoma development, while its role in OC remains to be explored." (PMID 32984052, 2020). "In hepatocellular carcinoma, DSCR8 increases Fzd7 expression by sequestering miR-485-5p." (PMID 34671643, 2021). "However, the exact expression, function, and mechanism of DSCR8 in hepatocellular carcinoma (HCC) remain uncovered." (PMID 30154476, 2018). "Conversely, DSCR8, an lncRNA known to activate WNT/β-catenin signaling in hepatocellular carcinoma, was confirmed to be massively induced by decitabine in MCF-7 cells by RT-qPCR." (PMID 35351824, 2022). "For example, LINC00638 promotes immune escape in hepatocellular carcinoma by sponging microRNA-4732-3p and targeting UL16-binding protein 1 (ULBP1), and the lncRNA Down syndrome critical region 8 (DSCR8) interacts with microRNA-137 to facilitate gastric cancer progression." (PMID 35587748, 2022).
ovarian carcinoma (5 papers, 2020 to 2024). A malignant neoplasm originating from the surface ovarian epithelium. "Interestingly, abnormal expression of DSCR8 is associated with poor prognosis in the liver and ovarian cancer." (PMID 34095215, 2021). "LncRNA DSCR8 is upregulated in ovarian cancer tissue and promoted tumour growth." (PMID 35004308, 2021). "Contrarily, it was shown that miR-98-5p is downregulated in ovarian cancer tissues, and its mitigative effects on cancer are hampered by overexpressed lncRNA DSCR8, which is known to promote cancer progression through a highlighted lncRNA DSCR8/miR-98-5p/STAT3/HIF-1α axis." (PMID 38872210, 2024). "Similarly, DSCR8 has been shown to be dysregulated in ovarian cancer." (PMID 33381546, 2020).
melanoma (4 papers, 2018 to 2024). A malignant, usually aggressive tumor composed of atypical, neoplastic melanocytes. "DSCR8 gene (Down syndrome critical region 8), also known as MMA-1 (Malignant melanoma-associated protein 1), is highly expressed in uterine cancer and melanoma." (PMID 38792557, 2024). "Among the top 20 upregulated genes were the alpha fetoprotein (AFP) gene, several genes of the melanoma antigen (MAGE) protein family, and other melanoma-associated genes (MAGE-A4, -10, -12, -B-2; DSCR8, PRAME)." (PMID 37592303, 2023). "Dysregulation of the lncRNA DSCR8 has been observed in uterine cancer, melanoma and liver cancer, and upregulation of ADARB2-AS1 has been detected in human epidermal growth factor receptor 2-positive BC." (PMID 34228637, 2021). "LncRNA DSCR8 is a newly identified non-coding RNA in uterine cancer and melanoma, which might be potential prognostic indicators and therapeutic targets in these cancers." (PMID 30154476, 2018).
gastric cancer (3 papers, 2021 to 2023). A primary or metastatic malignant neoplasm involving the stomach. "Other lncRNA including ELFN1-AS1, CASC9, SLCO4A1-AS1, DSCR8 and so on are all found to be studied previously and associated with at least one cancer type, which demonstrates that these lncRNAs can indeed capture the oncogenic features of gastric cancer." (PMID 34728653, 2021). "LncRNA DSCR8 mediates miR-137/Cdc42 to regulate gastric cancer cell proliferation, invasion and cell cycle as a competitive endogenous RNA." (PMID 37858131, 2023).
liver cancer (3 papers, 2021 to 2023). An epithelial or non-epithelial malignant neoplasm that arises from the liver. "LncRNA DSCR8 promotes the proliferation of liver cancer cells and inhibits apoptosis via the miR-22-3p/ARPC5 axis." (PMID 37858131, 2023).
uterine cancer (3 papers, 2018 to 2024). Primary or metastatic malignant neoplasm involving the uterine corpus and/or the cervix. "It is worth noting that, recently, lncRNA down syndrome critical region 8 (DSCR8) has been found to be dysregulated in uterine cancer and melanoma." (PMID 30154476, 2018).
breast carcinoma (1 paper, 2021). "We further selected five lncRNAs (DSCR8, TP53TG1, CBR3-AS1, LINC01006, HAGLROS) that were not previously reported to be related to the drug sensitivity of breast cancer and performed qRT-PCR to verify their expression levels." (PMID 33494806, 2021).
Down syndrome (1 paper, 2013). "For example, in Tc1 mouse livers, the bidirectional promoter of the Down’s Syndrome critical regions 4 and 8 (DSCR4 and DSCR8) is bound by Pol II, enriched for H3K4me3, and generates poly(A) transcripts." (PMID 23246434, 2013).
cancer (9 papers, 2020 to 2024). A tumor composed of atypical neoplastic, often pleomorphic cells that invade other tissues. "DSCR8 has been shown to be involved in the progression of cancer." (PMID 33381546, 2020). "Our research reveals that some of the DEirlncRNAs included in the modeling play vital roles in the malignant phenotype of many cancers, such as MYLK−AS1, THUMPD3 − AS1, and DSCR8, especially in the development of HCC." (PMID 34923955, 2021). "A number of these genes are known to be involved in cancer, including the downstream gene epidermal growth factor receptor (EGFR), the lncRNAs DSCR8 and ADARB2-AS1, and the TF heat shock factor 4 (HSF4)." (PMID 34228637, 2021). "To further confirm the functions of DSCR8 on cancer growth, we established the A2780 cell model with overexpressing DSCR8 and SKOV-3 with knocking down DSCR8 and conducted tumor xenograft in nude mice." (PMID 32984052, 2020). "Interestingly, known CTAs, such as MAGEA3, MAGEA1, DSCR8, MAGEC2, and MAGEA6, tended to be identified in the largest number of cancer types." (PMID 39561714, 2024).
tumor (6 papers, 2014 to 2023). "DSCR8 is also closely associated with various clinicopathological features of GC, including tumor size, metastasis, and tumor-node-metastasis (TNM) stage." (PMID 37670949, 2023). "It is worth mentioning how our study differs from previous studies in that we first linked DSCR8 with ARPC5 and added tumor suppressor miRNA, miR-22-3p, to make the axis complete." (PMID 36605483, 2023). "DSCR8, another lncRNA, promotes tumor cell progression in GC patients by acting as a miR-137 sponge and positively regulating Cdc42 expression." (PMID 37670949, 2023). "The results show that the volume and the growth rate of the tumor in nude mice decreased significantly after inhibiting the expression of DSCR8." (PMID 36605483, 2023). "It was found that overexpressing DSCR8 notably promoted tumor growth, while knocking down DSCR8 dampened tumor growth." (PMID 32984052, 2020). "Clinically, we found that DSCR8 and miR-485-5p were closely related to tumor size, TNM stage, venous invasion, 5-year overall survival, and 5-year disease-free survival of HCC patients." (PMID 30154476, 2018). "And we found that the median expression of DSCR8 was much higher in HCC tissues than that in non-tumor tissues (P < 0.001)." (PMID 30154476, 2018). "Therefore, miR-98-5p is a tumor-suppressive gene in OC, and DSCR8 promotes the progression of OC by inhibiting miR-98-5p." (PMID 32984052, 2020). "In the prognostic PRlncRNA risk model, 8 lncRNAs (HOTAIR, LINC00402, SFTA1P, LINC00461, DSCR8, CYP1B1-AS1, LINC00330, ALMS1-IT1) were upregulated, while the other 3 lncRNAs (ZRANB2-AS1, MYB-AS1, TP53TG1) were downregulated in tumor tissues." (PMID 35413978, 2022).
DSCR8 also shares sentences with these, for which no sentence is quoted: Leigh syndrome (1 paper); osteosarcoma (1).